TRPV1 (transient receptor potential cation channel subfamily V member 1)
Diseases named in the same sentence as TRPV1 in open-access papers (continued):
Sharing a sentence is not in itself a finding about the gene and the disease.
neurological diseases (13 papers, 2014 to 2026). "The dysregulation of TRPV1 is associated with the occurrence and development of many neurological diseases, making TRPV1 a potential therapeutic target for treatment." (PMID 38202764, 2023). "TRPV1 can modulate the primary and stimulus-induced release of pro-/anti-inflammatory cytokines and alleviate neurological diseases associated with inflammation." (PMID 31947713, 2020). "TRPV1 encodes for a key cation channel in nociception and is implicated in some neurological disorders." (PMID 27483351, 2016). "As expected, although some studies have shown that TRPV1 has pro-inflammatory effects, some experiments have indicated that TRPV1 plays a protective role in some neurological diseases." (PMID 38202764, 2023). "Certainly, TRPV1 also modulated the occurrence and development of numerous neurological disorders by regulating the inflammatory cytokines in the CNS." (PMID 31947713, 2020). "TRPV1 also modulated the occurrence and development of numerous neurological disorders by regulating the inflammatory cytokines in the central nervous system (CNS)." (PMID 31947713, 2020). "These suggest that TRPV1 is harmful in neurological diseases." (PMID 37404813, 2023). "TRPV1 was found to be playing critical roles in developing neurological diseases in fetuses." (PMID 36211461, 2022). "Therefore, TRPV-1 activation leads to aggravate the inflammatory response in certain neurological diseases (e.g., experimental autoimmune encephalomyelitis, epilepsy, and brain ischemia)." (PMID 30687006, 2018). "In contrast, other studies indicate a protective role of TRPV-1 in neurological diseases." (PMID 30687006, 2018). "To date, the functions of TRPV1 in the peripheral nervous system (PNS) were under comprehensive investigation and their potential application as a target for treating neurological disorders has been extensively demonstrated." (PMID 31947713, 2020). "In the current study, we aim to: (i) highlight a potential link between the eCB system and neurological disorders, (ii) assess if THC exposure alters the expression of eCB-related genes, and (iii) identify evolutionary-conserved residues in CB1R or TRPV1 in light of their function." (PMID 38404644, 2024). "Capsaicin, as a TRPV1 agonist, induces Ca2+ signaling in microglia mitochondria, production of mtROS, activation of MAPK, and increased chemotaxis activity in microglia, inducing immune and neurological diseases." (PMID 37404813, 2023).
bacterial infection (8 papers, 2014 to 2025). "Inflammation caused by bacterial infection has been reported to exacerbate AG-enhanced toxicity in the cochlea due to the upregulation of the AG-permeable cation channel TRPV1." (PMID 32235401, 2020). "However, loss of TRPV1 function has been associated with increased production of TNFα upon bacterial infection." (PMID 25242870, 2014). "Additionally, TRPV1 may be directly involved in pain and inflammation associated with bacterial infection." (PMID 38731999, 2024). "We demonstrate that TRPV1 has a significant function for myocardial injury imposed by bacterial infection." (PMID 34282193, 2021). "Especially for TRPV1, there are a couple of reports concluding that inhibition of TRPV1 neurons during bacterial infection results in a better prognosis." (PMID 34804016, 2021). "Novel and recent findings on its role indicate that the endogenous activation of TRPV1 protects mammals from bacterial infections." (PMID 31223430, 2019). "More recently, TRPV1 was suggested to modulate a range of macrophage-mediated responses to bacterial infection." (PMID 25242870, 2014). "Bacterial infections induce acidosis, and protons could directly gate TRPV1." (PMID 29295977, 2018). "However, it is important to highlight that capsazepine was administered in this study, as described by Fernandes and collaborators who showed that repeated treatment with this drug in vivo produces a similar profile to that of TRPV1 KO mice in response to bacterial infection." (PMID 25242870, 2014). "As lack of TRPV1 was previously shown to exacerbate hypothermia in mice with bacterial infection, mouse body temperatures were registered." (PMID 31223430, 2019). "Interestingly, although TRPV1 ablation exacerbates hypothermia in bacterial infection, it was found herein that TRPV1KO mice and WTs treated with the selective TRPV1 antagonist SB366791 are protected from this condition in comparison with infected WTs." (PMID 31223430, 2019).
psychiatric disorder (7 papers, 2020 to 2025). A disorder characterized by behavioral and/or psychological abnormalities, often accompanied by physical symptoms. "The need for selective TRPV1 inhibitors extends beyond pain treatment, to other diseases associated with this channel, including psychiatric disorders." (PMID 37117175, 2023). "A fact worth mentioning is also that TRPV1 is a potential therapeutic target for psychiatric diseases." (PMID 40283995, 2025). "It is conceivable that our findings could be useful in understanding disorders that involve TRPV1, and this channel may represent a compelling target for therapeutic agents against related psychiatric disorders." (PMID 32116530, 2020). "We propose that TRPV1, NAT and taurine are important for modulating synaptic activity in the PFC, and impairment in balance as well as disturbance in synaptic plasticity could be a pathogenic mechanism of psychiatric disorders." (PMID 32116530, 2020).
respiratory diseases (6 papers, 2006 to 2024). "Within recent years, pulmonary researchers have shown an interest in TRPV1 and the possible role of this receptor in respiratory diseases." (PMID 17173683, 2006). "Moreover, TRPV1 may have an increasing relevance as a target in respiratory diseases as inflammation becomes progressively chronic." (PMID 17173683, 2006). "Thus, the decrease in TRPA1, TRPV1, and MUC5AC in the lungs following the administration of LM extract should improve respiratory disease symptoms, such as cough and mucus production, in mice." (PMID 39519565, 2024).
gastrointestinal disorders (4 papers, 2015 to 2023). "Since TRPV1 has been implicated in gastrointestinal disorders including IBD, our data suggests a role for modulation of TRPV1 activity in the intestine beyond nociception, to regulate inflammation in a host beneficial manner that should be explored further." (PMID 38109366, 2023). "TRPV1 is involved in visceral hypersensitivity in gastrointestinal disorders including dyspepsia, too." (PMID 35566230, 2022). "Upregulated TRPV1 has been confirmed in various GIT diseases, including FDY." (PMID 35566230, 2022). "Thus, TRPV1 is in focus of new treatment approaches development and recent data suggest both natural and synthetic substances that affect TRPV1 as a potent treatment of various gastrointestinal disorders." (PMID 31263706, 2019).
kidney disease (4 papers, 2018 to 2025). "TRPV1 is widely known to play a pro-inflammatory role, but studies also point to its anti-inflammatory and protective roles in kidney diseases." (PMID 34201387, 2021). "Since PKCα is an important signaling molecule in kidney disease, we investigated whether it plays a downstream role in Ca2+-permeable TRPV1 after oxalate treatment." (PMID 34201387, 2021).
gastrointestinal tumor (3 papers, 2020 to 2025). "Therefore, TRPV1 channel seems to play a special role as GC suppressor because the aberrant expression and function of most Ca2+-permeable TRP channels are usually associated with GI tumor promotion." (PMID 33008449, 2020). "However, by using BM chimeras, we found that TRPV1 gain of function in hematopoietic cells, but not in epithelial cells, was critical to exacerbate colon inflammation." (PMID 33251043, 2020).
hematological malignancies (3 papers, 2022 to 2023). "Analysis of the crosstalk between TRPV1 with candidate proteins validated to influence fertility outcome showed that networks associated with cell death and survival, cellular compromise, hematological disease, and embryonic development were primarily affected by these TRP channels." (PMID 36211461, 2022). "To date, there has only been a limited assessment of TRPV1 expression in either normal blood cells or hematological malignancies." (PMID 35477804, 2022). "TRPV1 in patients with other hematological malignancies (n = 9) were all found to be similar to controls." (PMID 35477804, 2022). "Differential expression of TRPV1 in subsets of patients with different hematological malignancies with higher TRPV1 expression in some of these groups compared to normal blood." (PMID 35477804, 2022). "In conclusion, we provide an optimized flow cytometry method for routine expression analysis of clinical samples and show that TRPV1 is increased in a subset of patients with hematological malignancies." (PMID 35477804, 2022). "Using our optimized protocol, TRPV1 was detected in the PBMC fraction of all 49 patients with hematological malignancies, including B-NHL, MM, and a range of other malignancies." (PMID 35477804, 2022). "This is the first study to report an optimized method to detect TRPV1 expression using flow cytometry in hematological malignancies." (PMID 35477804, 2022). "The top scoring functional biological networks assigned to the selected DEPs and TRPV1 by IPA network analysis resulted in the identification of a network where 27 DEPs interacted with TRPV1, to regulate “Cell Death and Survival, Cellular Movement, Hematological Disease”." (PMID 36211461, 2022). "Here we show through in silico analysis that elevated TRPV1 mRNA expression occurs in a range of hematological malignancies and presents an optimized flow cytometry method to rapidly assess TRPV1 protein expression for both cell lines and primary patient samples." (PMID 35477804, 2022).
cardiac diseases (2 papers, 2020 to 2021). "Transient receptor potential vanilloid type 1 (TRPV1) is a non-selective cation channel, which is involved in the endogenous stress adaptation mechanism for protection of the heart as well as the occurrence and development of some heart diseases." (PMID 34040539, 2021). "Although the effect of activation of the TRPV1 channel on different types of non-neural cells in the heart remains unclear, most data show that stimulation of sensory nerves expressing TRPV1 or stimulation/overexpression of the TRPV1 channel has a beneficial role in heart disease." (PMID 34040539, 2021).
gastrointestinal disease (2 papers, 2016 to 2022). A disease that occurs in the gastrointestinal system, excluding the hepatobiliary system. "Our findings demonstrate a contribution of TNFR1, p38 MAPK and TRPV1 to TNFα‐induced sensitization of colonic afferents, highlighting the potential utility of these drug targets for the treatment of visceral pain in gastrointestinal disease." (PMID 35775903, 2022). "The TRPV1 channel also plays a role in systemic inflammation and protects the gastrointestinal tract againstinflammatory or functional gastrointestinal diseases." (PMID 27191606, 2016). "The TRPV1 channel islikely important in tissue protection and in the restoration of epithelial tissuebecause changes in TRPV1 expression are observed in response to several inflammatory orfunctional gastrointestinal diseases." (PMID 27191606, 2016).
blood cancers (1 paper, 2022). "Therefore, increased TRPV1 expression in blood cancers could create a new therapeutic target to treat these conditions." (PMID 35477804, 2022).
brain disorder (1 paper, 2022). A disease affecting the brain or part of the brain. "The diverse influences of TRPV1 channels in pathological condition may reflect cause or consequence of brain disorders." (PMID 35518644, 2022). "Finally, we discuss the putative contributions of TRPV1 in diverse brain disorders in order to expedite the development of next-generation therapeutic treatments." (PMID 35518644, 2022).
genetic disorders (1 paper, 2019). "We have also identified, for the firsttime, two TPV1 mutations in patients sufferingfrom a human pathology and, to our knowledge, TRPV1 has never been involved beforein any genetic disorders." (PMID 29930394, 2019).
movement disorder (1 paper, 2022). Neurological conditions resulting in abnormal voluntary or involuntary movement, which may impact the speed, fluency, quality and ease of movement. "However, in other studies, TRPV-1 agonists were found to not only inhibit the anti-movement disorder effect of OEA, but also improve movement disorder by decreasing the expression of movement disorder-related molecules." (PMID 35264932, 2022).
skeletal muscle disorder (1 paper, 2022). A disease involving the skeletal muscle tissue. "Overall, this study reveals a new critical cross-talk between S1P and eCB systems in skeletal-muscle cells, identifying the Ca2+ channel TRPV1 as a pivotal target and thus opening the avenue to new molecular approaches to control skeletal-muscle disorders characterized by calcium dyshomeostasis." (PMID 36232401, 2022).
TRPV1 also shares sentences with these, for which no sentence is quoted: Seizure (5 papers); skin cancer (5); chronic prostatitis (3); herpes zoster (3); Hypercholesterolemia (3); immune dysfunction (3); infarction (3); trigeminal neuralgia (3); adenocarcinoma (2); autonomic dysfunction (2); brain injuries (2); Coma (2); complex regional pain syndrome (2); dementia (2); diabetic retinopathy (2); Hyperinsulinemia (2); keloid (2); multiple myeloma (2); muscle disorders (2); neuralgia (2); neuritis (2); neuroendocrine tumor (2); oral lichen planus (2); postherpetic neuralgia (2); prurigo nodularis (2); subarachnoid hemorrhage (2); acute monocytic leukemia (1); acute myeloid leukemia (1); acute myocardial infarction (1); age (1).
A further 96 diseases each share a sentence with TRPV1 in 1 paper.